DAO (D-amino acid oxidase)
Diseases named in the same sentence as DAO in open-access papers (continued):
Sharing a sentence is not in itself a finding about the gene and the disease.
schizophrenia (continued). "In the same vein, the expression and activity of DAO are significantly increased in patients with schizophrenia." (PMID 34658976, 2021). "This review summarizes the roles of d-amino acids and pLG72, also known as d-amino acid oxidase activator, on two neurodegenerative disorders, schizophrenia and Alzheimer’s disease (AD)." (PMID 34681579, 2021). "The peroxisomal enzyme D-amino acid oxidase (DAO) is highly expressed in the kidney, liver, and brain in mammals and plays a critical role in the pathophysiology of schizophrenia." (PMID 33133125, 2020). "The significant Kruskal-Wallis test was shown for DAO, G72, and melatonin levels (P = 3.12 × 10–9, 2.2 × 10–16, and 3.35 × 10–6, respectively) between schizophrenia patients and healthy controls." (PMID 32582679, 2020). "The mean level of DAO protein in the plasma of schizophrenia patients was considerably higher than that of healthy controls (37.64 ± 14.18 ng/mL vs. 28.03 ± 9.84 ng/mL; P = 5.55 × 10–9)." (PMID 32582679, 2020). "TAK-831 is a highly selective and potent inhibitor of D-amino acid oxidase (DAAO) currently under clinical development for schizophrenia." (PMID 32901384, 2020). "In recent years, trials of sodium benzoate, a D-amino acid oxidase inhibitor, have been contacted for the treatment of mild AD, autism, schizophrenia, resulting in symptomatology improvement of patients." (PMID 33126852, 2020). "In particular, add-on therapy with a DAO inhibitor, sodium benzoate, improves schizophrenia symptomatology, even in clozapine-resistant patients." (PMID 29976992, 2018). "Studies have also shown increased DAO activity in brains of schizophrenia patients compared to the healthy controls." (PMID 29114206, 2017). "One possible explanation for NMDA receptor hypofunction theory proposed in schizophrenia is increased DAO activity leading to decreased D-serine which subsequently causes hypofunction of the NMDA receptors." (PMID 29114206, 2017). "Previous studies have shown evidence for significant association of nucleotide variations at DAO and DAOA locus with schizophrenia and bipolar disorder." (PMID 29114206, 2017). "One of the possible explanations for NMDA receptor hypofunction theory proposed in schizophrenia is probably an increased activity of DAO leading to decreased D-serine." (PMID 28428746, 2017). "Encouragingly, improved cognition was recently observed in both patients with schizophrenia and dementia in early clinical trials involving the administration of the DAO inhibitor sodium benzoate." (PMID 26833794, 2016). "In patients with schizophrenia, adjunctive treatment with the DAO inhibitor sodium benzoate was effective against a range of symptom domains, including cognition, in a small 6 week randomized clinical trial." (PMID 25816902, 2015). "Evidence that DAO contributes to the glutamatergic dysfunction in schizophrenia is threefold: it may be a susceptibility gene; DAO expression and activity are increased; and DAO inhibitors show preliminary preclinical and clinical evidence for therapeutic efficacy." (PMID 24822045, 2014). "The rationale for DAO inhibitors as a treatment for schizophrenia has come from their potential to increase D-serine availability, thus correcting the postulated NMDA receptor co-agonist deficiency." (PMID 24822045, 2014). "DAO shows genetic association with amyotrophic lateral sclerosis (ALS) and schizophrenia, in whose pathophysiology aberrant metabolism of D-serine is implicated." (PMID 24959138, 2014). "Interest has grown in the role of DAO in several neuropsychiatric disorders, especially schizophrenia, a disorder in which NMDA receptor-related hypofunction is pathophysiologically implicated and is a target of much therapeutic research." (PMID 24822045, 2014). "Computational tools combined with experimental testing were used to identify novel inhibitors of hDAAO (human D-amino acid oxidase), an enzyme relevant for schizophrenia and neuropathic pain." (PMID 25001371, 2014).
schizophrenia (continued). "Nevertheless, the present findings draw attention to the possible interaction between DAO and the dopamine system, which has potential relevance for the ongoing development of DAO inhibitors to treat schizophrenia and other disorders." (PMID 24822045, 2014). "DAO inhibitors are under development as a therapy for schizophrenia, a disorder involving both NMDA receptor and dopaminergic dysfunction." (PMID 24822045, 2014). "Genetic studies of schizophrenia show that the susceptibility gene G72 plays a role in regulation of D-amino acid oxidase (DAO), an enzyme that is upregulated in schizophrenia." (PMID 25004141, 2014). "The secondary analyses instead confirmed effects of the DAO, PPP3CC, and DTNBP1 genes on schizophrenia susceptibility; these effects were mediated not only by the gender and paranoid/non-paranoid dichotomy but also by epistatic/interaction mechanisms." (PMID 23497497, 2013). "Although the important role of G72 on DAO regulation has been suggested, the specific role G72 plays in regulating DAO activity in patients with schizophrenia is controversial." (PMID 24362575, 2013). "The factors regulating D-serine are important for understanding normal NMDA receptor function and because D-serine, along with DAO and SRR, is implicated in the pathogenesis and treatment of schizophrenia." (PMID 20091774, 2010). "In the case of schizophrenia, a population-based analysis has revealed four genes, DAAO (DAO), DAOA, DTNBP1 and NRG1, to be associated with the schizophrenia." (PMID 19379523, 2009). "We also conclude that the lack of demonstrable G72 expression in relevant brain regions does not support a role for G72 protein in modulation of DAO activity and the pathology of schizophrenia via a DAO-mediated mechanism." (PMID 19077230, 2008). "We also conclude that the lack of demonstrable G72 expression in relevant brain regions does not support a role for G72 in modulation of DAO activity and the pathology of schizophrenia via a DAO-mediated mechanism." (PMID 19077230, 2008). "This casts doubt on the proposed G72 protein modulation of DAO activity, which has been suggested to contribute to the pathology of schizophrenia." (PMID 19077230, 2008). "In schizophrenia, d-amino acid oxidase mRNA was increased in the cerebellum, and as a trend for protein." (PMID 17880399, 2007). "The direction of change in DAO mRNA and protein in the cerebellum in schizophrenia was consistent between the two brain series, but the increase in schizophrenia appeared more marked in the London series." (PMID 17880399, 2007). "Similarly, a recent study evaluating the D-amino acid oxidase (DAAO) inhibitor luvadaxistat demonstrated a significant improvement in MMN amplitude at a 50-mg dose in patients with schizophrenia, consistent with enhanced NMDAR function." (PMID 40701342, 2025). "Therefore, inhibition of d-amino acid oxidase (DAAO) has the potential to be a new therapeutic approach for the treatment of schizophrenia." (PMID 37289348, 2023). "Luvadaxistat, a D-amino acid oxidase (DAAO) inhibitor that increases the glutamate co-agonist D-serine levels, is being developed for the treatment of cognitive impairment associated with schizophrenia." (PMID 36928351, 2023). "In addition, the stimulation of the DAO enzyme has shown enhanced symptoms in rodent models with schizophrenia, and an increased DAO activity seems most likely to impact the D-Serine metabolism." (PMID 35225861, 2022). "The research found that excessive DAO expression would exacerbate schizophrenia." (PMID 35990602, 2022). "A transcript of DAO has been detected in higher quantities in the schizophrenia-cerebellum." (PMID 35225861, 2022). "Furthermore, it has been revealed that DAO and G72/G30 are implicated as key proteins in the NMDA receptor signaling pathway for schizophrenia." (PMID 35225861, 2022).
schizophrenia (continued). "However, the use of compounds such as D-serine for treating schizophrenia is inhibited by its limited availability in the central nervous system due to its metabolism by the flavoenzyme D-amino-acid oxidase (DAAO)." (PMID 34903265, 2021). "The glutamate hypothesis of schizophrenia suggests that increased DAO activity leads to decreased D-serine levels, which may subsequently lead to NMDAR hypofunction." (PMID 34658976, 2021). "The D-amino acid oxidase (DAO) protein and its interaction partner, the D-amino acid oxidase activator (DAOA, also known as G72) protein, have been implicated as two key proteins in the N-methyl-D-aspartate receptor (NMDAR) pathway for schizophrenia." (PMID 32582679, 2020). "In line with this hypothesis, studies have demonstrated that supplementing antipsychotic drugs or d-amino acid oxidase inhibitors with d-alanine shows promise for treatment of schizophrenia." (PMID 32867295, 2020). "Interestingly, reduction of DAO activity, through the increase of endogenous D-Ser levels, has been suggested as a pharmacological tool for ameliorating schizophrenia symptoms." (PMID 29976992, 2018). "DAO degrades D‐serine, a coagonist of the NMDA receptor, and is associated with schizophrenia." (PMID 29943428, 2018). "We assessed the potential effect of DAO and DAOA SNPs on DAO and DAOA expression to understand whether such genetic variations known to be risk factors in schizophrenia play a role in the regulation of their expression." (PMID 28428746, 2017). "Furthermore, in a postmortem study the activity of DAO was found to be two-fold higher in schizophrenia subjects." (PMID 28654017, 2017). "DAO and DAOA are susceptibility genes for schizophrenia and bipolar disorders." (PMID 28428746, 2017). "The NMDA receptor hypofunction theory proposed in schizophrenia might be partly explained by increased DAO activity modulated by DAOA leading to decreased d-serine, a co-agonist of NMDA receptors." (PMID 29326614, 2017). "Another study found a negative association of DAO rs3918346 with neurocognitive functioning in schizophrenia patients." (PMID 29326614, 2017). "The glutamate hypothesis of schizophrenia has proposed that increased DAO activity leads to decreased D-serine, which subsequently may lead to N-methyl-D-aspartate (NMDA) receptor hypofunction." (PMID 29114206, 2017). "DAO and DAO activator (DAOA) have been suggested as candidate genes for schizophrenia." (PMID 26986737, 2016). "With regard to the association between genotypes and other endophenotypes of schizophrenia, one study found that an SNP in the 5’-UTR in DAO (rs4623951) was associated with sensorimotor gating, working memory, and personality patterns in healthy males in a Greek population." (PMID 26986737, 2016). "Convergent evidence implicates DAO in the pathophysiology and potential treatment of schizophrenia." (PMID 25816902, 2015). "Consequently, DAO inhibitors are currently under development for the treatment of schizophrenia, and there is already some evidence that testifies to their efficacy." (PMID 25816902, 2015). "Given that DAO is overactivated in schizophrenia, D-serine and dopamine being modulated by DAO may constitute a new aspect of a model of aberrant glutamatergic and dopaminergic neurons in schizophrenia." (PMID 24959138, 2014). "All existing licensed drug treatments for schizophrenia are dopamine D2 receptor antagonists, and the question arises whether DAO inhibitors may also work, at least partly, via dopaminergic effects." (PMID 24822045, 2014). "In particular DAO, PPP3CC, and DTNBP1, might be differentially involved in schizophrenia susceptibility according to gender and gene interaction mechanisms." (PMID 23497497, 2013). "The discrepancies between the primary and the secondary analyses may be reconciled assuming that the DAO, PPP3CC, and DTNBP1 genes modulate the susceptibility for schizophrenia only under definite circumstances." (PMID 23497497, 2013).
schizophrenia (continued). "Given the effect of oestradiol in reducing DAO activity in the liver tissues of female guinea pigs, oestrogens could have a protective effect on schizophrenia by preventing increases of DAO activity and subsequent NMDA hypofunction." (PMID 23497497, 2013). "Although the results are preliminary and needed replication in a larger sample, this study suggests that NMDA receptor-mediated signalling genes (DAO, PPP3CC, DTNBP1) might be involved in schizophrenia pathogenic mechanisms related to gender." (PMID 23497497, 2013). "For example, DAO inhibitors may provide a valuable therapeutic strategy to improve schizophrenia symptoms due to low NMDA function." (PMID 24362575, 2013). "Besides, we have also performed the association studies in Taiwanese samples on NRG1 (8p12), DAO (12q24), and DAOA (12q33.2) as these three genes were reported to have strong association with schizophrenia in the literature." (PMID 23555897, 2013). "Genome wide association studies of schizophrenia published to date do not further implicate DAOA or DAO." (PMID 19586533, 2009). "Furthermore, it has been proposed that the G72 peptide is a direct modulator of DAO activity and as such has mechanistic relevance to schizophrenia." (PMID 19077230, 2008). "For these studies, we used immunohistochemistry and in situ hybridization and focused on areas of relevance to schizophrenia and where DAO is reputed to be abundant or important, namely the dorsolateral prefrontal cortex (DPFC), hippocampus, cerebellum and substantia nigra." (PMID 17880399, 2007). "Altered d-serine in schizophrenia may be explained, in part, by involvement of the d-serine catabolic enzyme d-amino acid oxidase (DAO, also abbreviated to DAAO)." (PMID 17880399, 2007). "Nevertheless, this variability does raise the issue of the general applicability of the findings; inspection of the raw data shows that the increased cerebellar DAO immunoreactivity and mRNA in schizophrenia, whilst seen in both the London and Oxford series, was more apparent in the former." (PMID 17880399, 2007). "We studied d-amino acid oxidase and serine racemase immunohistochemically in several brain regions and compared their immunoreactivity and their mRNA levels in the cerebellum and dorsolateral prefrontal cortex in schizophrenia." (PMID 17880399, 2007). "Thus, future studies exploring the tolerability and efficacy profile in specific disease subgroups, in addition or not to other drugs enhancing the D-amino acid pathway, will shed light on the real potential of DAO inhibitors in schizophrenia and other psychotic disorders." (PMID 35883465, 2022). "Furthermore, both reduced brain serine racemase (SRR) and increased DAO protein levels may contribute to a decrease in CSF D-serine levels in schizophrenia." (PMID 34575878, 2021). "Indeed, when DAO inhibitors such as sodium benzoate have been used to treat schizophrenia and early-stage Alzheimer’s disease they have been found to produce improvements in neurocognitive functioning, as an adjunct to improvements in symptoms of clinical pathology." (PMID 33570017, 2021). "Thus, inhibitors of DAO have been suggested as a therapeutic option for schizophrenia." (PMID 26686055, 2016). "D-amino acid oxidase (DAO) has been found to be involved in the signal transduction pathway of the N-methyl-D-aspartic acid (NMDA) receptor and has been hypothesized to be implicated in the pathogenesis of schizophrenia." (PMID 26986737, 2016). "DAO inhibitors could therefore prove useful in the treatment of schizophrenia." (PMID 25816902, 2015). "Consequently, NMDA dysfunction and its related pathological symptoms of schizophrenia may result from overexpression of G72 that changes DAO activity." (PMID 24362575, 2013). "Nevertheless, the presence of DAO in these neurons suggests that it may play a role in dopaminergic function and, speculatively, the involvement of dopamine or dopamine–glutamate interactions in schizophrenia." (PMID 17880399, 2007).
schizophrenia (continued). "The administration of a DAO inhibitor, such as 5-chloro-benzo[d]isoxazol-3-ol (CBIO), in a preclinical model of schizophrenia enhanced D-serine efficacy in mice." (PMID 37107350, 2023). "A review of D-serine's safety is timely and pertinent, as D-serine remains under active study for schizophrenia, both directly (R61 MH116093) and indirectly through D-amino acid oxidase (DAAO) inhibitors." (PMID 34447324, 2021). "However, a recent genome-wide association study conducted by the Psychiatric Genomics Consortium found that out of 108 schizophrenia-associated loci, none were within DAO and DAOA gene regions (Schizophrenia Working Group of the Psychiatric Genomics Consortium, 2014)." (PMID 28428746, 2017). "We also do not have schizophrenia brain samples to comment on regulation and expression of DAO and DAOA mRNA and protein across different brain regions in schizophrenia." (PMID 28428746, 2017). "This study demonstrated increased expression in schizophrenia of SRR in the DPFC, and of DAO in the cerebellum." (PMID 17880399, 2007). "Our second objective was to extend the current data regarding altered expression of DAO and SRR in schizophrenia." (PMID 17880399, 2007). "DAO has been of interest in psychiatry because its major substrate in the brain is D-serine, which modulates NMDAR functions and contributes to NMDAR hypofunction in schizophrenia." (PMID 34658976, 2021). "In this review, we focus on describing preclinical and clinical studies of direct and indirect GMS modulators in the treatment of schizophrenia, including glycine, D-cycloserine, D-serine, glycine transporter 1 (GlyT1) inhibitors, and D-amino acid oxidase (DAO or DAAO) inhibitors." (PMID 34658976, 2021). "D-amino acid oxidase is a catalyzing flavoprotein in the oxidative deamination of neutral D-amino acids, and the inhibition of DAAOs can augment NMDAR function as a treatment for schizophrenia." (PMID 33912003, 2021). "DAO and DAOA genes are alleged to be involved in pathophysiology of neuropsychiatric disorders such as schizophrenia and bipolar disorder, but the interactions between these genes remains unclear to date." (PMID 29114206, 2017). "At present there are no drugs on the market to treat the negative symptoms and cognitive deficits of schizophrenia, and clinical trials with DAO inhibitors or D-serine have not shown a conclusive or strong effect in schizophrenia." (PMID 29114206, 2017). "Given that d‐serine is an NMDAR co‐agonist, the overactivity of DAO (and resulting insufficiency of d‐serine) could contribute to the NMDAR hypofunction proposed to exist in schizophrenia." (PMID 25816902, 2015). "The biological functions of DAO and DAOA are involved in the hypothesized hypofunction of NMDA receptor complex as the potential pathogenesis of schizophrenia." (PMID 23555897, 2013). "The primary analyses did not demonstrate associations between schizophrenia and any of the 32 studied DAOA, DAO, PPP3CC, and DTNBP1 SNPs." (PMID 23497497, 2013). "Between-gene interactions including DAO*DISC1,DAO*NRG1 and DAO*RASD2 and a within-gene interaction for CACNG2 were found among schizophrenia subjects with severe sustained attention deficits, suggesting a modifying effect of impaired neuropsychological functioning." (PMID 23555897, 2013). "Initial reports suggested G72 as an activator of D-amino acid oxidase (DAO), supporting the glutamate dysfunction hypothesis of schizophrenia." (PMID 19077230, 2008). "In the DPFC, DAO mRNA normalized to r18s was unchanged in schizophrenia (Mann–Whitney U-test, P = 0.33) as was DAO mRNA normalized to GAPDH (data not shown)." (PMID 17880399, 2007). "If DAO contributes to NMDAR hypofunction in schizophrenia, then presumably it does so via enhancement (rather than impairment) of DAO function, as this will promote d-serine degradation and thence decreased d-serine occupancy of NMDARs." (PMID 17880399, 2007).